INS (insulin)
Diseases named in the same sentence as INS in open-access papers (continued):
Sharing a sentence is not in itself a finding about the gene and the disease.
Hypoglycemia (continued). "Frequency of hypoglycemic symptoms and duration during insulin induced hypoglycemia." (PMID 39629677, 2024). "It is important to point out that although metformin therapy leads to a decrease in insulin concentration, it does not alter the secretory profile in any way and does not cause hypoglycemia; on the contrary, it maintains euglycemia." (PMID 38540265, 2024). "Reactive hypoglycaemia in the postprandial state (sometimes referred to as glucose dips) typically occurs 2–3 h after a meal and is thought to be primarily due to insulin-stimulated peripheral glucose uptake superseding the increase in exogenous (meal-derived) glucose appearance rates." (PMID 39231870, 2024). "Conversely, fear of hyperglycaemia can lead to over-use of insulin and more frequent hypoglycaemia." (PMID 38795153, 2024). "Therefore, inappropriate insulin secretion by neoplastic cells leads to hypoglycemia and increased concentrations of insulin-antagonistic counterregulatory hormones and associated clinical signs." (PMID 39595353, 2024). "The fear of hypoglycemia has been cited as a reason for delaying insulin boluses." (PMID 39457586, 2024). "Different counteractive strategies may be used by children with T1DM or their parents in order to avoid hypoglycemia due to their fear, including increased intake of carbohydrates, avoidance of physical activity, and administering less insulin than required." (PMID 38607611, 2024). "InsAb with high binding capacity and low affinity is rare, albeit identifying this group of patients is relevant because these antibodies can bind with a large amount of insulin and rapid release of this hormone, significantly affecting glycemic control, including episodes of morning hypoglycemia." (PMID 39767558, 2024). "In addition to direct costs related to glucose monitoring, insulin administration, and hypoglycemia management, indirect costs and long-term implications must be considered." (PMID 38476508, 2024). "SGLT2i also decrease insulin resistance, blood pressure and body mass, while not causing hypoglycemia." (PMID 39140033, 2024). "The combination of a DPP-4 inhibitor with insulin is particularly attractive because it does not significantly increase the risk of hypoglycemia, as the insulin secretagogue effect is glucose-dependent." (PMID 40066124, 2024). "A reduction in insulin dosage could alleviate injection-related adverse reactions; reduce the degree of weight gain, hypoglycemia, and hyperinsulinemia; and thus improve PIR." (PMID 38803476, 2024). "Hypoglycaemia incidence was less with 5 or 15 mg Tirzepatide versus basal insulin." (PMID 38665722, 2024). "The most common serious adverse effect of insulin is hypoglycemia." (PMID 39300573, 2024). "NICTH is defined as hypoglycaemia that is induced by a tumour other than insulinoma and IGF-II is the major cause of NICTH which can be diagnosed with elevated IGF-II levels, low or low normal insulin levels." (PMID 39651031, 2024). "Conversely,increasing insulin dose before steady state is reached could result in overinsulinizationand induce hypoglycemia." (PMID 38224978, 2024). "Finally, AI-enabled decision aid in the form of smartphone application alerted type 1 diabetic patients either when their insulin doses were due and/or 30 min before a hypoglycaemia event was likely to occur." (PMID 39572838, 2024). "Although the risk of hypoglycemia is generally low for GLP-1 RAs, dose modifications of concomitant insulin and/or sulfonylureas may be required." (PMID 38592214, 2024). "A hypoglycemia workup was initiated two days after receiving the last dose of insulin." (PMID 39347250, 2024). "However, we also discerned a positive link between high within-day GV fluctuations and the use of sulfonylurea, insulin, and glinide due to their heightened hypoglycemia risks." (PMID 38429847, 2024). "By using IV insulin, significant hypoglycemia and hypokalemia continue to be areas of concern." (PMID 39130949, 2024).
Hypoglycemia (continued). "Unlike other antidiabetic drugs, metformin does not promote the secretion of endogenous insulin, and so it does not cause hypoglycemia or hyperinsulinemia." (PMID 39459443, 2024). "The muscles tend to be more insulin sensitive for 1 to 2 days after exercise, leading to an increased risk of hypoglycemia, but this is not implemented in the game." (PMID 38713496, 2024). "One noted that the convenience was especially useful for individuals who need more frequent monitoring, such as those at higher risk of hypoglycemia, as the CGM allowed them to feel more confident taking their insulin while avoiding their blood glucose dropping too low." (PMID 39405528, 2024). "During an episode of hypoglycemia (serum glucose 33) the patient had a suppressed insulin level of <1 μU/mL (reference: 3-25), C-peptide <0.5 ng/mL (reference: 1.1-4.3), β-hydroxybutyrate level <1.0 (reference: <3), and random cortisol of 23 (reference: morning 8-25)." (PMID 39372824, 2024). "Furthermore, it does not appear that oxidative stress plays a central role in neuronal damage following severe insulin-induced hypoglycemia." (PMID 39004753, 2024). "During fasting, the balance between insulin and glucagon is crucial in preventing hypoglycemia." (PMID 39149119, 2024). "Our study showed that insulin Gla-300 maintained the glycemic control of T2DM patients who decided to fast during the holy month of Ramadan without increasing the risk of hypoglycemia." (PMID 37581325, 2024). "In this study we set out to examine changes in side-dependent renal net glucose release (SGN) through unilateral low-frequency stimulation (LFS) of the renal plexus with a pulse generator (2–5 Hz) during normoglycemia (60 min) and insulin-induced hypoglycemia ≤3.5 mmol/L (75 min) in seven pigs." (PMID 38396718, 2024). "This amplified signal was transmitted to β‐cells through MNs and effectively triggered insulin secretion for modulating the blood glucose levels without causing potential risks of hypoglycemia." (PMID 37899686, 2024). "After the exclusion of exogenous insulin intake, the hyperinsulinemia with conserved C-peptide level, in a hypoglycemic context, associated with strongly positive free AIA and the presence of insulin-antibody complexes, were evocative of an autoimmune origin of the hypoglycemia." (PMID 39071705, 2024). "Some SAPs include a feature for automatic insulin suspension to avert hypoglycemia." (PMID 38846748, 2024). "Clinical diagnosis of hyperinsulinism is confirmed by inappropriately elevated insulin, elevated C-peptide, and suppressed β-hydroxybutyrate levels at the time of hypoglycemia, with resolution of symptoms after glucose administration, satisfying the diagnostic criteria known as the Whipple triad." (PMID 39170749, 2024). "However, insulin therapy has several drawbacks, including hypoglycemia, weight gain, injection site reactions, inconvenience, and cost." (PMID 38920672, 2024). "If a sulfonylurea or insulin is needed, there may be less hypoglycemia with addition of glargine, compared to addition of glimepiride." (PMID 39546502, 2024). "In summary, our organismal analyses together with our ex vivo studies provide striking parallels and converging lines of evidence that TRPC5 activity at the level of chromaffin cells constitutes a crucial step in the homeostatic counter-regulation of insulin-induced hypoglycemia." (PMID 39375537, 2024). "Metformin precisely lowers hepatic gluconeogenesis without boosting insulin secretion, lead to weight gain, or raise the risk of hypoglycemia." (PMID 38302935, 2024). "The concentration of GABA, as measured by microdialysis, in VMH extracellular fluid has been shown to be higher and did not significantly decrease with the onset of acute hypoglycemia in rats subjected to insulin mediated recurrent hypoglycemia as compared to normoglycemic controls." (PMID 38323079, 2024).
Hypoglycemia (continued). "Additionally, a more robust hypoglycemia challenge was used to assess ZT-01 (12 U/kg insulin, achieving blood glucose in controls <3.0 mmol/L), compared to PRL-2903 (3 U/kg, achieving glucose values of 3.5 mmol/L in controls)." (PMID 38510652, 2024). "Exenatide ER provided short-term glycemic improvements and weight loss, especially in those with some residual insulin production, without raising the risk of hypoglycemia." (PMID 39273299, 2024). "Consequently, this increase leads to inhibiting pancreatic insulin secretion and stimulating hepatic gluconeogenesis and glycogenolysis, resulting in hypoglycemia and an increase in insulin requirement." (PMID 39685874, 2024). "This can include changes in brain responses to hypoglycemia that may exacerbate hypoglycemia due to reduced insulin-antagonistic reactions." (PMID 39532813, 2024). "In the first trimester, there is an increased risk of hypoglycemia, and women may experience reduced awareness of hypoglycemia due to altered insulin needs." (PMID 38592281, 2024). "In mouse models of insulin-induced hypoglycemia, intraperitonealadministration of glucagon-micelles successfully regulated blood glucoseconcentration, both reverting and preventing deep hypoglycemia dependingupon when the glucagon-micelles were injected relative to insulinadministration." (PMID 39634211, 2024). "The results indicated that weekly icodec resulted in better glycemic control with fewer basal insulin injections and lower bolus insulin doses, without increasing the risk of hypoglycemia, in comparison to daily glargine U100." (PMID 38672255, 2024). "He visited our department for hypoglycemia with abnormalities in insulin secretion." (PMID 37204622, 2024). "Additionally, approximately 70% of women who use insulin during pregnancy experience episodes of hypoglycemia." (PMID 39335553, 2024). "On the other hand, patients who do not yet use sensors but plan to do so anticipate that these will contribute to the reduction and prevention of hypoglycemia episodes, improvement in the adjustment of insulin doses, greater flexibility in daily activities, and also fewer stings." (PMID 39376804, 2024). "The insulin infusion rate must also be closely proportional to the amount of glucose obtained from food because an excessive infusion of exogenous insulin leads to a hypoglycemia situation." (PMID 38186949, 2024). "Finally, with regard to drug interactions, while initiating TZP, a dose reduction of concomitantly administered insulin or insulin secretagogues (e.g., sulfonylureas) should be carefully considered to avoid hypoglycemia." (PMID 39329873, 2024). "However, it is unclear which insulin analog affects GV and hypoglycemia better in patients with insulin-dependent type 1 diabetes." (PMID 38541176, 2024). "In overweight and obese T1D patients, liraglutide significantly improves glycemic control, promotes weight loss, and lowers insulin requirements without increasing the risk of hypoglycemia." (PMID 39273299, 2024). "Secretion of vasopressin is stimulated by insulin and by hypoglycemia." (PMID 39769071, 2024). "Most hypoglycaemia might otherwise be induced due to inadequate insulin administration, such as inadequate reduction of insulin infusion rates by insulin infusion pumps." (PMID 38542818, 2024). "Small RCTs in adults with T2D have shown dramatic improvement in glucose outcomes compared to standard insulin therapy without an increased risk of hypoglycemia." (PMID 39390689, 2024). "Consequently, we started treatment with fluids containing dextrose to prevent hypoglycemia while offering this substrate for use by the tissues when insulin was administered." (PMID 39420895, 2024). "These interventions may reduce hypoglycemia symptoms by inducing gluconeogenesis, reducing insulin secretion, or mitigating the initial hyperglycemic peak, which mainly treats the symptom, but not the cause." (PMID 39153140, 2024).
Hypoglycemia (continued). "Our data demonstrate that prone positioning does not meaningfully increase the risk of hypoglycaemia, but does increase insulin demand." (PMID 39532941, 2024). "In turn, insulin is released in response to glucose, and so the hypoglycemia that the fetus faces at high altitude may result in reduced fetal insulin levels." (PMID 38694168, 2024). "Tight control over insulin production is necessary to protect against hypoglycemia and may reflect physiologic autoregulation of beta cell mass in healthy animals." (PMID 39433176, 2024). "Secondly, we classified medication according to hypoglycaemia risk as determined by the Dutch guidelines and considered switching from insulin to any non-insulin medication as de-intensification." (PMID 39407915, 2024). "Several factors contribute to nonadherence to insulin, including pain associated with injections, fear of hypoglycemia and weight gain, interference of injections with daily routines and embarrassment associated with administering insulin in public." (PMID 39020348, 2024). "However, in real life, exercise-related hypoglycemia is frequently encountered in individuals treated with insulin, but a detailed description of its hemostatic consequences remains." (PMID 38642404, 2024). "However, in view of multiple episodes of hypoglycemia, even with very low doses of insulin, weight gain, and the appearance of acanthosis nigricans during follow-up, the possibility of T2DM or MODY was considered." (PMID 39420905, 2024). "It is essential that healthcare professionals provide intensive initial education for T1DM (blood glucose monitoring, insulin injections, dosing titration in special circumstances, management of hypoglycemia, carbohydrate counting, dietary and lifestyle modifications, etc.)." (PMID 39408305, 2024). "Despite this, hypoglycemia remains the primary side-effect of insulin therapy." (PMID 38894740, 2024). "In contrast, icodec (RR 1.31, 95% CI: 0.94 to 1.84) and BIF (RR 1.41, 95% CI: 0.74 to 2.70) did not demonstrate a significant reduction in hypoglycemia risk compared to daily insulin." (PMID 39335457, 2024). "The advantages of using insulin pumps are multiple, starting from better glycemic control through more efficient adjustments of the amount of insulin delivered, decreasing the frequency of hypoglycemia, and increasing the quality of life of T1D patients." (PMID 38396657, 2024). "Hypoglycemia also occurs in late-stage type 2 diabetes (T2D), particularly when insulin therapy is initiated, but the utility of SSTR2 antagonists in ameliorating hypoglycemia in this disease state is unknown." (PMID 38510652, 2024). "The lower risk of non-severe hypoglycaemia and less weight gain associated with insulin detemir resulted in economic benefits in the short term." (PMID 38694591, 2024). "Results of RCTs suggest that it is possible to switch from a basal bolus insulin regimen to a combination of BI plus either a GLP-1 RA or a SGLT2i, with same or better glycemic control, less injections, less insulin doses, less hypoglycemia and increased satisfaction of therapy." (PMID 38767675, 2024). "After establishing a significant burden of hypoglycaemia in the initial observation period, a requirement for hourly capillary blood glucose monitoring (for up to 6 h) following the administration of insulin for hyperkalaemia was incorporated into the guidelines." (PMID 38871123, 2024). "Generally, the risk of hypoglycemia is related to prandial and premixed bolus insulin therapy rather than basal insulin." (PMID 38213906, 2024). "Traditional therapies for sulfonylurea-induced hypoglycemia often involve intravenous and oral dextrose and glucagon, which may lead to recurrent hypoglycemia due to their stimulatory effects on insulin release." (PMID 39347364, 2024).
Hypoglycemia (continued). "Glycemic parameters within the reference interval of non-diabetic dogs (i.e., glycemia between 70 and 120 mg/dL, absent glycosuria) can be assumed as a trend to diabetic remission or insulin overdosing and therefore imply the possibility of episodes of hypoglycemia." (PMID 38539988, 2024). "The potential for hypoglycemia poses a significant concern with insulin injections." (PMID 38969701, 2024). "In contrast, hypoglycemia concern and time for judgment of the insulin-dose adjustments could have delayed the achievement of effective insulin doses within this cohort before full-term pregnancy." (PMID 38539988, 2024). "Prevention of hypoglycemia remains an unmet need for those receiving insulin therapy." (PMID 38510652, 2024). "The fact that level 1 and level 2 hypoglycemia occurred less often in the 12 h following IV insulin discontinuation was reassuring and may encourage practice change to early glargine administration." (PMID 39136541, 2024). "In addition, there was a decrease in overall hypoglycemia and an improvement in the level of satisfaction during this insulin treatment." (PMID 38982528, 2024). "Since amino acids also promote the release of insulin, it is hypothesized that the purpose of the increase in glucagon release is to physiologically prevent hypoglycemia following protein consumption." (PMID 39337311, 2024). "Administering too much basal insulin or not adjusting the dose properly can increase the risk of hypoglycaemia without reducing postprandial glucose excursions." (PMID 38337336, 2024). "Although these tests were not done on our patient due to study constraints, other non-insulin-induced hypoglycemia diagnostic criteria, such as reduced insulin levels and undetectable C-peptide, were present." (PMID 39138498, 2024). "Glucose is the primary fuel to the brain, and therefore a central energy deficit induced by 2DG triggers the glucose counterregulatory responses including endocrine and feeding responses in rats in a similar way as insulin-induced hypoglycaemia, thereby increasing blood glucose levels." (PMID 38392992, 2024). "However, persistent hypoglycemia can occur due to insulin overuse, poor gluconeogenesis, or failure of these counterregulatory mechanisms." (PMID 39006567, 2024). "Therefore, this study was conducted regarding the NLEM in Thailand to assess the financial impact of different adoption rates of IGlar treatment instead of conventional insulin treatment for patients with T2D and severe hypoglycemia." (PMID 39877917, 2024). "Patients with glucokinase (GCK) HI may develop ketotic hypoglycemia with prolonged fasting, in contrast to the hypoketotic hypoglycemia usually found in HI, especially in the setting of glucose levels dropping below the altered threshold for insulin secretion." (PMID 37454648, 2024). "Thus, the outcomes indicate that metformin is more efficient than glyburide and insulin in managing glucose levels in the blood, minimizing macrosomia, decreasing birth weight, and reducing the occurrence of infant hypoglycemia." (PMID 39479091, 2024). "The insulin doses usually need to be decreased to avoid hypoglycemia." (PMID 38785359, 2024). "The ICV infusion of insulin in doses that do not cause systemic hypoglycemia increased the secretion of AVP in a dose-dependent manner." (PMID 38279313, 2024). "In a recent study, oral insulin regulated the blood sugar levels without causing hypoglycemia, supporting the optimal pharmacodynamic effect of exogenous plant protein drugs." (PMID 39861664, 2024). "Despite this treatment, hypoglycemia often recurs or may last longer as glucose is a potent stimulus for releasing more preformed insulin." (PMID 39347364, 2024).